STAT3 (signal transducer and activator of transcription 3)
Diseases named in the same sentence as STAT3 in open-access papers (continued):
Sharing a sentence is not in itself a finding about the gene and the disease.
breast cancer (continued). "Overall, our study indicates that N-linked glycosylation of PD-L1 is required for the ability of PD-L1 to induce cell-autonomous pro-metastatic activities in breast cancer cells, mainly by regulating the activation of STAT3 and STAT1." (PMID 37830552, 2023). "Walsh and his colleagues found that RECK can participate in metastasis of breast carcinoma via regulation of STAT3‐dependent switch." (PMID 37795791, 2023). "Another SH2 domain inhibitor, STA-21, reduced breast carcinoma cells’ survival, characterized by STAT3 overactivation." (PMID 38067351, 2023). "Another in vivo study reported reduced STAT3 expression levels in DATS treated breast cancer xenografts in mice." (PMID 37021043, 2023). "In vitro melanoma and mammary carcinoma models were used and showed a down-regulation of STAT3 by specific ASOs, which inhibited gene expression and down-regulated the STAT3 target gene vascular endothelial growth factor." (PMID 36614305, 2023). "Further, it has been explored that C15:0 has an inhibitory effect on the IL-6-induced JAK2/STAT3 signaling pathway in human breast carcinoma cells, considering C15:0 as a promising therapeutic strategy to treat human cancers." (PMID 37432205, 2023). "In breast cancer, miR-124 directly regulates STAT3 expression to reduce breast cancer stem cell resistance to doxorubicin." (PMID 36295083, 2022). "Recent studies have also confirmed that CCL5/CCR5 can affect the polarization of M2 macrophages through the MEK/STAT3 signaling pathway in luminal B breast cancer." (PMID 36033472, 2022). "We examine the latest research into the therapeutic targeting of IL-6 family cytokines that inhibit STAT3 transcriptional activity as a potential breast cancer treatment, including current clinical trials." (PMID 35053592, 2022). "At a molecular level, S6 appeared to occupy an important pocket of SOST to block its interaction with STAT3 in breast cancer cells." (PMID 36581888, 2022). "CD36 expression promotes breast cancer by increasing STAT3 signaling and beta oxidation, providing energy for growing breast cancer cell." (PMID 35888767, 2022). "The literature and clinical study evidence highlight a clear role for IL-6 and IL-11-induced STAT3 activation in driving pro-tumorigenic processes and metastatic dissemination in all types of breast cancer." (PMID 35053592, 2022). "Secreted factors of human MSCs isolated from umbilical cords were shown to suppress tumor progression and increase radiosensitivity through downregulating intra-tumoral STAT3 signaling in a xenograft mouse model and in breast cancer cell lines." (PMID 36010901, 2022). "Three models of BALB/c nude mice were orthotopically xenografted with mouse breast cancer 4T1 cells expressing different levels of Stat3 (4T1-GFP control group, 4T1-Knockout-Stat3 group and 4T1-Overexpress-Stat3 group)." (PMID 35628154, 2022). "The STAT3 signal is closely associated with the EMT in many kinds of cancers, including breast cancer, gastric cancer, colorectal cancer as well as LAC." (PMID 35216134, 2022). "While there is clear potential for targeting STAT3 and its activating cytokines as a therapeutic strategy for breast cancer, limitations of this approach also need to be considered." (PMID 35053592, 2022). "Breast cancer cell-derived exosomes transfer gp130 to macrophages in vitro, which alters macrophage polarization by activating the STAT3 pathway." (PMID 36499561, 2022). "It is reported that JAK/STAT3 signaling pathway plays critical roles in progression of many human solid tumors such as breast cancer, ovarian cancer and OSCC." (PMID 35909161, 2022). "Previous studies have revealed the role of STAT3 activation in promoting glycolysis in breast cancer by upregulation of PKM2." (PMID 36188586, 2022). "For example, AUF inhibits STAT3 and telomerase activity in MDA-MB-231 breast cancer cells and induces the apoptosis of multiple myeloma cells through both down-regulation of STAT3 and inhibition of NF-κB activity." (PMID 36230784, 2022).
breast cancer (continued). "VEGF can bind to VEGF receptor 2 (VEGFR2) to activate the STAT3 pathway as well as to increase Myc and Sox-2 expression to enhance the stemness of the breast cancer cells." (PMID 35805056, 2022). "Polyphenols extracted from Artemisia annua can inhibit the phenotype of CSC, mediate the phosphorylation of MMP-9 and STAT3, and exhibit anticancer effects in human breast cancer cells." (PMID 36686745, 2022). "Among the first reported Statinhibs was STA-21, which was shown to inhibit STAT3 dimerization, DNA binding, and STAT3-dependent transcription in breast cancer cells." (PMID 35663932, 2022). "Specifically, IL-6, IL-11, their receptors and downstream transcription factor STAT3, are known to be highly expressed in breast cancer, and the role of cytokine-induced STAT3 signaling in the breast tumor microenvironment is multifaceted." (PMID 35053592, 2022). "Its downregulation has also been associated with a reduced growth of different breast cancer cell subtypes, thus suggesting an interest in the STAT3 inhibitor as a potential anticancer or adjuvant strategy for breast cancer." (PMID 36140359, 2022). "IL-6R is involved in the IL-6/IL-6R/STAT3 signaling pathway, whose role in breast cancer progression has been extensively demonstrated." (PMID 35406622, 2022). "At the same time, phosphorylation and dephosphorylation play a crucial role in the regulation of the activities of CD44 and Stat3, and aberrant phosphorylation of CD44-Stat3 is linked with various tumor progressions, such as NPC, breast cancer and lung cancer." (PMID 36678534, 2022). "Circulating FABP4 functions as a tumor-promoting factor for obesity-related breast cancer through the IL-6/STAT3/ALDH1 pathway." (PMID 36060264, 2022). "Because STAT3 is constitutively active in the majority of breast cancers and plays an important role in mediating breast cancer growth, migration, and metastasis, this review will focus on the IL-6/JAK/STAT3 signaling cascade." (PMID 35371975, 2022). "Next, IHC was used to evaluate the correlation between the expression of LIF in adipocytes adjacent to breast cancer and Stat3 phosphorylation in breast cancer tissues." (PMID 35280694, 2022). "According to the data gathered from several studies, the JNK/STAT3 signaling pathway is activated in the progression of various tumors, such as lung cancer, breast cancer, and CRC." (PMID 35215376, 2022). "Conversely, activating phosphorylation of STAT3 at Ser727 significantly triggers hepatoma cell survival, and p-STAT3 (Ser727) accelerates breast cancer growth via exacerbating ROS accumulation." (PMID 36443287, 2022). "This review will focus on the role of IL-6 and IL-11, in particular, in driving increased STAT3 transcriptional activity in breast cancer, and how this leads to metastasis and immune evasion within the tumor microenvironment." (PMID 35053592, 2022). "Studies have shown that dapansutrile can inhibit the IL6/STAT3 axis to inhibit breast cancer metastasis." (PMID 36105284, 2022). "It is also important to note that transmembrane C-terminal MUC1 (MUC1-c) is necessary for Tyr705-Stat3 phosphorylation in breast cancer cells and promotes Stat3-mediated transcription in an auto-inductive regulatory loop." (PMID 36017196, 2022). "The emerging role of IL-6/JAK/STAT3 in promoting the breast CSC subpopulation and breast cancer metastases in vivo underscores the therapeutic potential in exploiting the IL-6/JAK/STAT3 signaling axis in metastatic breast cancer." (PMID 35371975, 2022). "Many signaling pathways are overactive in breast cancer, and among them is the STAT3 signaling pathway." (PMID 35053592, 2022). "Signal transducer and activator of transcription 3 (STAT3) was found to bind its response elements in the HER2 promoter to upregulate HER2 transcription in metastatic HER2-positive breast cancer." (PMID 35795053, 2022). "It is a signaling regulator and transcription activator STAT3, which is considered a specific oncogene for breast cancer." (PMID 36362406, 2022).
breast cancer (continued). "The role of STAT3 expression is different and its link to prognosis varies between ER(+) and ER(−) breast cancer." (PMID 35314590, 2022). "The adipocyte-derived IL-6 was reported to promote breast cancer metastasis by inducing PLOD2 expression through activating the JAK/STAT3 and PI3K/AKT signaling pathways." (PMID 35924148, 2022). "IL-6 and IL-8 secreted from adjacent cells in the TME such as TAMs activate the STAT3 signaling pathway in breast cancer cells." (PMID 35847899, 2022). "In clinical breast cancer pathology samples, the up-regulation of LIF in paracancerous adipose tissue was positively correlated with the activation of Stat3 in breast cancer." (PMID 35280694, 2022). "LIF was highly expressed in adipocytes adjacent to breast cancer of clinical breast cancer specimens, which was correlated with Stat3 phosphorylation in breast cancer." (PMID 35280694, 2022). "Zerumbone, a sesquiterpenoid and cyclic ketone, suppressed EGF-dependent CD44 expression through inhibition of the STAT3 pathway in breast cancer cell lines (SKBR3 and MDA-MB468)." (PMID 35785191, 2022). "Bazedoxifene inhibits STAT3-mediated transcriptional activity and, in turn, suppresses breast cancer colony formation, migration, and invasion." (PMID 35371975, 2022). "Whilst results for this study remain to be evaluated, there is much scope for the further exploration of small molecule STAT3 inhibition in a clinical breast cancer setting." (PMID 35053592, 2022). "Another study on the MDSCs isolated from breast cancer patients revealed that STAT3 inhibition and TLR7/8 pathway stimulation in MDSCs repolarize and suppress MDSCs of breast cancer patients." (PMID 36476317, 2022). "Overall, modulating IL-6/IL-6Rα interaction shows promising results in all subtypes of breast cancer mediated by IL-6/JAK/STAT3 signaling." (PMID 35371975, 2022). "As a downstream gene of STAT3, c-myc was found to be related to the drug resistance of breast cancer cells." (PMID 35154350, 2022). "STAT3 activation is most prominent in breast cancer tissues and is found to be elevated in greater than 40% of breast cancer cases, making it a promising molecular target in the development of new TNBC therapies." (PMID 35053370, 2022). "In this study, we also found that paeoniflorin enhances the inhibitory effect of tamoxifen on STAT3 activation in ER + breast cancer cells." (PMID 35154350, 2022). "It is of note that the self-secreted tumor-derived factors (TDFs) IL-6, VEGF, and G-CSF can stimulate the STAT3 cascade in myeloid cell differentiation, impairing DCs generation and function in breast cancer TME." (PMID 35745800, 2022). "The co-overexpression and physical interaction of phospho-STAT3 and GLI1, the glioma-associated oncogene, is found in approximately 60–70% of both TNBC and HER2-enriched breast cancers." (PMID 35053592, 2022). "Stattic has been used to antagonize STAT3 in various disease models including osteoarthritis and Breast Cancer." (PMID 35524286, 2022). "It is known that STAT3 plays a major role as a regulator of resistance to chemotherapy in breast cancer." (PMID 35955836, 2022). "Several SH2-containing proteins are involved in the development of certain types of cancers, such as breast cancer (Grb2, Grb7, STAT3, and Src), liver cancer (STAT3), Prostate cancer (STAT3, STAP2), Chronic Myelogenous Leukemia, CML (Bcl/Abl)." (PMID 36555586, 2022). "For instance, DDR1-mediated STAT3 activation is required for bladder tumor cell colonization to the lung and for metastatic reactivation of breast cancer cells." (PMID 34941574, 2022). "For example, niclosamide is currently FDA-approved as an anti-parasitic drug, yet treatment exhibited inhibition of IL-6-induced STAT3 activation resulting in suppression of adipocyte-induced EMT in breast cancer cells." (PMID 35371975, 2022).
breast cancer (continued). "Breast cancer cells can hijack the IL-6/JAK/STAT3 signaling to evade normal immune responses and further promote tumor growth by activating surrounding microenvironmental cells." (PMID 35371975, 2022). "STAT3-mediated IP3R3 downregulation in the ER was a major factor in anti-apoptotic effects of breast cancer cell lines." (PMID 36231093, 2022). "IL-6 and phosphorylated-STAT3 (phospho-STAT3, pSTAT3) are co-overexpressed in primary breast cancer specimens." (PMID 35371975, 2022). "For example, in one study, breast cancer patients had reduced IL6-driven STAT3 phosphorylation in CD4+ T cells." (PMID 35270020, 2022). "IP3R3 stabilization in breast cancer cells is further regulated by an ER-localized constitutively active form of the oncogenic transcription factor signal transducer and activator of transcription 3 (STAT3)." (PMID 36158205, 2022). "Taken together, the IL-6/JAK/STAT3 pathway is a major regulator of breast cancer metastasis through promoting breast cancer cell proliferation, EMT, enriching the breast CSCs, and suppressing apoptosis." (PMID 35371975, 2022). "Breast cancer cells and CSCs highly express IL-8 after chemotherapy leading to the formation of an inflammatory loop between NF-kB and STAT3 signaling pathways." (PMID 35505363, 2022). "In contrast, blockade of NF-κB and STAT3 is reported to reduce tumor escape from immunosurveillance, decreasing growth, and the spread of breast cancer." (PMID 35890318, 2022). "Our findings from HUVEC tube formation studies depicted that TAM derived IL-6 promotes angiogenesis either directly or by inducing angiogenic potential of breast cancer cells via STAT-3 pathway." (PMID 35300689, 2022). "In contrast to tight regulation in mammary epithelial cells, Stat3 signaling in breast cancer is dysregulated, and, although indirect, it is active downstream of ERBB2 and RET." (PMID 35044452, 2022). "In breast cancer, Stat3 is more often overactive in TNBCs than other types and has been implicated in inducing CSC properties." (PMID 36017196, 2022). "More recently, it has become widely accepted IL-6 mediates an oncogenic role in multiple cancers, including breast cancer, primarily through the activation of STAT3." (PMID 35371975, 2022). "The functional relevance of the CD44s isoforms has been highlighted in malignancies other than colon cancer, namely in prostate and breast cancer where it activates, among others, PDGFRβ/Stat3 and Akt signaling to promote EMT and CSC traits." (PMID 36346211, 2022). "In this study, we detected the alterations in ERK1/2 and STAT3 activation when CKAP2 level was changed in breast cancer cells, suggesting the potential involvement of these two signaling pathways, which awaits detailed characterization in future studies." (PMID 35853854, 2022). "Since breast cancer cells mediate their paracrine pro-carcinogenic effects through the IL-6/STAT3 pathway, we tested the effect of exogenous recombinant human IL-6 (rIL-6)." (PMID 36359766, 2022). "IL-10 and STAT3 are involved in the occurrence and development of several diseases, such as AD, breast cancer, glioma, and autosomal dominant hereditary high lgE syndrome." (PMID 35572136, 2022). "There are attempts to combine CDK4/6 inhibitors with MEK inhibitors (for RAS-driven cancers) or PI3K inhibitors (for breast cancer), but to our knowledge this study is the first to propose the use of E2F/STAT3 inhibitor combination for GBM treatment." (PMID 35058574, 2022). "GSEA of public breast cancer patient databases confirmed that IL-6/JAK/STAT3 signaling was significantly correlated with PD-L1 expression." (PMID 35927628, 2022). "In patients with breast cancer, STAT3 has several key roles in tumor development and progression, as shown by numerous studies." (PMID 35327992, 2022). "Many studies documented that STAT-3-mediated breast cancer metastasis happens through the upregulation of MMP9, TWIST, SNAIL and SLUG expression." (PMID 36431925, 2022).
breast cancer (continued). "Previous studies have reported that activation of STAT3 is related to PD-L1 expression in various cancers, including breast cancer." (PMID 35927628, 2022). "Another study found that the application of stilbenes, such as resveratrol and pterostilbene, can silence tumour suppressor genes in breast cancer tissues via acetylated transcription factor STAT3." (PMID 36557789, 2022). "This complex also decreased the expression of STAT3 in murine breast cancer cells and decreased the expression of STAT3 targeted genes." (PMID 35897737, 2022). "Pre-clinical in vitro and in vivo studies have identified a number of candidate small molecule inhibitors that target the STAT3 signaling cascade, namely gp130, JAK and STAT3 itself, which inhibit growth and invasion of breast cancer models." (PMID 35053592, 2022). "In turn, STAT3 increases TIMP-1 secretion by breast cancer cells, leading to a TIMP-1/CD63/integrin β1/STAT3 positive feedback loop, which can be further fueled by IL-6." (PMID 36291767, 2022). "Administration of Bcl-2 antagonist, sabutoclax, concurrently suppresses IL-6/STAT3 signaling to resensitize chemoresistant breast cancer cells to chemotherapeutic agents." (PMID 35371975, 2022). "We found that, like in CLL and breast cancer, in MF fibrocytes and LDCs phosphorylated STAT3 binds to and activates the GLI1 gene promoter." (PMID 35595725, 2022). "Preclinical studies provide functional evidence of STAT3 playing a critical role in the metastatic dissemination of breast cancer cells to distal sites, namely to bone, liver and lung." (PMID 35053592, 2022). "We further demonstrate that TAM derived IL-6 induces CSC enrichment in breast cancer via STAT3 pathway." (PMID 35300689, 2022). "In prostate cancer, glioma, endometrial cancer, and breast cancer, the IL-6/gp130/STAT3 signaling pathway has been demonstrated to be involved in the regulation of CSC properties such as self-renewal, stemness marker expression, and tumor cell growth." (PMID 35565185, 2022). "This nanomedicine effectively decreased tumor growth and angiogenesis both in vitro and in breast cancer xenografts by impacting the signal transducer and activator of the transcription 3 (STAT3)/vascular endothelial growth factor (VEGF) signaling axis." (PMID 35626078, 2022). "Immunoprecipitation assays provided evidence that lncRNA H19 regulated the expression of STAT3 (Signal transducer and activator of transcription 3) gene in breast cancer." (PMID 36685962, 2022). "OSM can also further activate IL-6/JAK/STAT3 signaling both in vitro and in vivo to promote breast cancer progression." (PMID 35371975, 2022). "Our results indicated that LIF plays an important role in CAA-mediated migration and invasion of breast cancer cells by regulating the activation of Stat3." (PMID 35280694, 2022). "The results of our study revealed that CPT is capable of suppressing JAK2 and STAT3 phosphorylation in breast cancer cells and its combination with naringenin exerts as additive effect on JAK/STAT pathway." (PMID 35606804, 2022). "Additional novel STAT3 inhibitors that have been investigated preclinically for the treatment of breast cancer include: LLY17, 6Br-6a, napabucasin, and coumarin-benzo[b]thiophene 1, 1-dioxide conjugates." (PMID 35371975, 2022). "It was reported that the activation of IL-6/JAK2/STAT3 pathway promotes proliferation, invasion, metastasis and angiogenesis, and inhibits apoptosis in breast cancers." (PMID 36431925, 2022). "Studies have shown that the expression of STAT3 protein is related to poor prognosis of lung cancer, breast cancer, liver cancer, colorectal cancer, and prostate cancer." (PMID 35463085, 2022). "TTI-101 is a novel small molecule STAT3 inhibitor, and is in a Phase I clinical trial examining pharmacokinetics and compound safety in advanced breast cancer patients as well as patients with unresectable solid tumors (NCT03195699)." (PMID 35371975, 2022).